CSF1 (colony stimulating factor 1)
Diseases named in the same sentence as CSF1 in open-access papers (continued):
Sharing a sentence is not in itself a finding about the gene and the disease.
prostate carcinoma (42 papers, 2009 to 2025). A carcinoma that arises from epithelial cells of the prostate gland. "Previously, we found that tumor-associated macrophages (TAM) can be recruited by CSF-1 secreted by docetaxel-treated prostate cancer cells and promote the survival of cancer cells in response to chemotherapy." (PMID 34069563, 2021). "Moreover, we showed that the expression of numerous genes was increased by CSF-1 in prostate cancer cells, including the spp1 gene that encodes for osteopontin, a major actor in prostate carcinogenesis." (PMID 36555673, 2022). "CSF-1 signaling is known to drive invasiveness and increase metastasis, and increased expression of CSF-1 is correlated with poor prognosis in ovarian, breast, and prostate cancer patients." (PMID 40646332, 2025). "In prostate cancer, docetaxel-treated cells secrete CSF-1 to recruit TAMs, which then activate CXCR4 signaling via CXCL12 secretion, promoting tumor cell survival and resistance to chemotherapy." (PMID 40433363, 2025). "Of particular interest, we also detected increased secretion of colony-stimulating factor-1 (CSF1) in prostate cancer cells overexpressing ST6GAL1." (PMID 38772281, 2024). "Another inhibitory effect of RT in prostate cancer is related to the activation of macrophage colony-stimulating factor 1 (CSF1)." (PMID 37173782, 2023). "CSF1 promotes migration of tumor-infiltrating myeloid cells (TIMs), and was found to be elevated in prostate cancer patients receiving RT." (PMID 37173782, 2023). "We showed that osteopontin transcript expression was increased by CSF-1 both in murine and human prostate cancer cells." (PMID 36555673, 2022). "In this context, abnormal expression of the receptor of Macrophage Colony-Stimulating Factor-1 (M-CSF or CSF-1) has been described in prostate cancer cells." (PMID 36555673, 2022). "In prostate cancer, colony-stimulating factor 1 (CSF1) significantly enhances the recruitment of tumor-associated macrophages (TAMs) and MDSCs." (PMID 36139006, 2022). "This prompted us to investigate the expression of spp1/osteopontin in CSF-1-stimulated prostate cancer cells." (PMID 36555673, 2022). "All together and in agreement with those obtained in murine cells, these results confirmed the functionality of CSF-1R in prostate cancer cells and osteopontin as a downstream target of CSF-1 signaling in these cells." (PMID 36555673, 2022). "Since CXCL12 is a classical ligand of CXCR4 and CSF-1/CSF-1R crosstalk from prostate cancer cells to recruited macrophages was previously identified, we proposed that the feedback crosstalk from macrophages to cancer cells is partly mediated by CXCL12/CXCR4." (PMID 34069563, 2021). "Conventional fractionation leads to transcription of colony-stimulating factor 1 (CSF1), which when blocked in prostate cancer models reduces TAM recruitment." (PMID 33050580, 2020). "ADT-induced prostate cancer cells express CSF-1 and other cytokines that significantly increase M2 TAM infiltration and potentially cause castration-resistant cancer progression." (PMID 32824865, 2020). "ADT induced an increased expression of colony-stimulating factor 1 (CSF1) in prostate cancer cells (PCs), leading to a significant enhancement of TAM infiltration." (PMID 31504033, 2019). "Escamilla and coworkers found that CSF1 was significantly induced in the prostate cancer cells by ADT, leading to a significant increase in TAM." (PMID 31504033, 2019). "The molecular mechanism of RT-induced CSF1 upregulation was recently described in a mouse prostate carcinoma." (PMID 28348554, 2017). "An increase in the levels of serum CSF1 was observed in prostate cancer patients receiving radiotherapy, suggesting that the radiation-induced CSF1 upregulation is clinically relevant." (PMID 28348554, 2017). "Five SNP-SNP interactions in three gene pairs (MMP16+ ROBO1, MMP16+ CSF1, and MMP16+ EGFR) were identified to be associated with aggressive prostate cancer in both groups." (PMID 23593148, 2013).
prostate carcinoma (continued). "Furthermore, CXCL5 and colony stimulating factor 1 (CSF-1) are associated with macrophage-driven bone metastasis Cyclooxygenase-1 (COX-1) positive macrophages can play an important role in prostate cancer bone metastasis." (PMID 38464516, 2024). "For example, photon radiotherapy of prostate cancer may produce a variety of chemokines, such as colony stimulating factor 1 (CSF1) and CXCL5, which promote the aggregation of MDSCs to tumors." (PMID 36138265, 2023). "Thus, OPN is one example of how prostate cancer cells, via the CSF-1/CSF-1R axis, are able to remodel the extracellular matrix and the immune landscape." (PMID 36555673, 2022). "In this study, we showed that, by directly influencing the localized accumulation of TAM with a soluble CSF-1 decoy receptor expressed by transfusion of exogenous CEPs, a reduction in the proliferative index and vascularity of tumors is accompanied by direct suppression of prostate cancer growth." (PMID 19522014, 2009). "Within the prostate cancer TME, tumor cells release a range of cytokines and growth factors, such as colony-stimulating factor 1 (CSF-1) and IL-4, which promote the polarization of macrophages toward the M2 phenotype." (PMID 40563466, 2025). "We next compared the transcriptome profiling of prostate cancer cells stimulated or not by CSF-1 for 24 h or 48 h." (PMID 36555673, 2022). "Clinical studies in prostate cancer demonstrated that overexpression of colony-stimulating factor (CSF-1) and its receptor (CSF1R or c-FMS), were responsible for monocyte and macrophage expansion, indicating poor prognosis in primary prostate cancers and development of bone metastasis." (PMID 26459393, 2015). "Although there is no report on a role of CSF1 in prostate cancer, previous studies reported overexpression of serum CSF1 in tumors of several cancer sites, including breast, ovary, and endometrial tissues." (PMID 23593148, 2013). "The anti-CSF-1 antibody LY302285 (IMC-CS4) also resulted in liver enzyme elevations and minimal efficacy in a phase I dose-escalation trial in solid tumors, and minimal toxicity in a second study in patients with refractory breast and prostate cancer, with a best response of stable disease." (PMID 39625569, 2025). "Interestingly, prostate cancer-derived EVs transfer CSF-1, VEGFA, MCP1, RUNX2, and FGF2 transcripts within recipient OBLs, but only CSF-1 content is significantly increased in the recipient cells, suggesting a mechanism controlling the selective use of EVs-cargo molecules in recipient OBLs." (PMID 33869035, 2021). "Importantly, some CSF-1 or CSF-1R inhibitors are already available and are in clinical trials for the treatment of advanced carcinoma, e.g. LY3022855 (IMC-CS4) (NCT01346358, phase I: metastatic breast and prostate cancer); PLX 3397 (NCT01596751 phase Ib/II: metastatic breast cancer)." (PMID 26098772, 2015). "Excitingly, our data shows that upregulation of ST6GAL1 in prostate cancer cells significantly increases expression of CD206 on macrophages, suggesting a shift toward a more immunosuppressive M2 phenotype (Two-way ANOVA, p < 0.0001) which was not dependent upon CSF1." (PMID 38772281, 2024).
atherosclerosis (41 papers, 2008 to 2025). A disease characterized by the build-up of fatty material and calcium deposition in the arterial wall resulting in partial or complete occlusion of the arterial lumen. "Studies have shown that CSF1 deficiency decreases the number of monocytes in peripheral blood and tissues, enhances macrophage apoptosis, and significantly inhibits atherosclerosis." (PMID 36523490, 2022). "CD26+ fibroblasts exhibited significant enrichment in genes linked to macrophage alternative activation, notably Csf1, underscoring their potential role in modulating inflammation and sustaining atherosclerosis through the recruitment, differentiation, and survival of macrophages." (PMID 39975362, 2025). "Unsupervised DEGs analysis of SMCs revealed increased expression in Abcb8ECKO of TGF-β-pathway genes such as Tgfb1, Tgfb2, Tgfb3, Mmp2 and Col1a1, inflammatory genes such as Ccl2 (encoding for MCP1) and Csf1 as well as atherosclerosis-associated genes including Egr1, Sqstm1, Irf1, Sox4 and Xylt1." (PMID 41252867, 2025). "CSF-1, known as macrophage colony-stimulating factor is a primary driver of macrophage expansion in atherosclerosis." (PMID 37794467, 2023). "Multiple studies have shown that CSF1 can be actively expressed in atherosclerotic lesions and plays a role in atherosclerosis formation." (PMID 36561774, 2022). "CSF1 has been shown to be involved in atherosclerosis development via stimulating differentiation, growth, and survival of monocytes/macrophages." (PMID 36139494, 2022). "Their inflammatory nature seems to be supported by the fact that osteopetrotic mice, which lack functional CSF1 (Colony Stimulating Factor 1) and therefore monocytes, are protected against hypercholesterolemia-induced atherosclerosis." (PMID 39649554, 2020). "In the context of an inflammatory disease, such as atherosclerosis however, deletion of CSF-1 results in dramatically reduced atherosclerotic plaque size." (PMID 30349538, 2018). "The proliferation rate of these cells can be enhanced by CSF-1/M-CSF and/or IL-4 under conditions of helminth infection, a healing response, atherosclerosis and possibly other types of inflammation." (PMID 24723924, 2014). "Beyond their critical physiological role, CSF-1 dependent macrophages have also been demonstrated to promote disease progression in conditions ranging from cancer to atherosclerosis and arthritis." (PMID 22505929, 2012). "Taken together, these results identify plausible candidate TFs that drove the phenotypic differences in SPP1+ foamy macrophages and indicate that the presence of CSF1+ mast cells may drive the phenotype of SPP1+ foamy macrophages in atherosclerosis." (PMID 36855107, 2023). "Thus, the effect of CSF1 on the development of atherosclerosis is likely due to regulating monocyte/macrophage function." (PMID 36139494, 2022). "Mice subjected to sleep fragmentation produced less hypocretin (a wake-promoting neuropeptide) in the lateral hypothalamus, which increased the expression of colony-stimulating factor-1, stimulated monocyte differentiation into macrophages, and ultimately accelerated atherosclerosis." (PMID 36291296, 2022). "Indeed, the pathophysiological importance of CSF-1-stimulated macrophage migration has recently been demonstrated in several diseases, including tumour invasion and metastasis, inflammatory arthritis and atherosclerosis." (PMID 22505929, 2012). "CSF1 can contribute to atherosclerosis development via fatty streak formation and progression to complex fibrous lesions, and CD44 may enhance atherosclerosis pathogenesis via reactive oxygen species, whereas neuregulin and ERBB4 are necessary for vascular growth and development." (PMID 18987747, 2008). "For example, Csf1−/− mice, which lack macrophage colony stimulating factor (M-CSF, also known as CSF1) are less prone to developing atherosclerosis." (PMID 31653058, 2019).
atherosclerosis (continued). "Some of them, such as colony-stimulating factor-1 (CSF-1) and monocyte chemoattractant protein-1 (MCP-1), whose partial or complete deletion dramatically reduces atherosclerosis in murine models despite severe hyperlipidemia, are important in the initial phases of plaque formation." (PMID 31448091, 2019).
pancreatic cancer (41 papers, 2013 to 2025). "At the transcript level, mRNA expression of Ccl2, Ccl7, Cxcl1, Cxcl3, and Csf2 was markedly downregulated in Ccn1‐deficient pancreatic tumors, whereas Cxcl5, Csf1, and Csf3 expression remained unchanged, and Ccl20 mRNA was elevated." (PMID 40287974, 2025). "The aggressive natures of pancreatic tumors are associated with the deactivation of stromal PSCs induced by CSF1 as well as with the mesenchymal nature of PDAC cells induced by SMAD3." (PMID 36038612, 2022). "Combination of radiotherapy with CSF-1 monoclonal antibody changed the phenotype of macrophages in pancreatic tumors, enhanced the effect of T cells, and slowed down the growth of tumor." (PMID 40007537, 2025). "In experimental PDAC models, CSF1/CSF1R signalling in pancreatic tumours depletes CD206Hi TAMs and reprograms remaining macrophages to support anti‐tumour immunity." (PMID 38501838, 2024). "Another study on pancreatic cancer showed that α-SMA+ CAF cells produce macrophage colony-stimulating factor 1 (M-CSF-1), IL-6, TGF-β, and CCL2 to promote monocyte recruitment and macrophage polarization into M2 macrophages." (PMID 39030445, 2024). "In pancreatic cancer models, the reprogramming of TAMs through colony-stimulating factor 1 (CSF1)/colony-stimulating factor 1 receptor (CSF-1R) blockade enhances the response to T-cell checkpoint immunotherapy." (PMID 38835055, 2024). "The blockade of CSF-1/CSF-1R activation can be a promising approach in pancreatic cancer therapy via reducing the TAM population, using combinative partners of standard treatment and immunotherapeutic agents." (PMID 33505964, 2020). "TAMs and MDSCs are recruited to the tumor stroma by high levels of colony-stimulating factor 1 (CSF-1) secreted from pancreatic tumor cells." (PMID 33383713, 2020). "Anti-CSF-1 therapy alters the tumor immune microenvironment by removing macrophages and reducing M2 infiltration, which is a useful therapeutic target in pancreatic cancer treatment." (PMID 33505964, 2020). "Blockade of CSF-1/CSF-1R axis in a pre-clinical mouse model of pancreatic cancer metastasis impaired macrophage recruitment and induced a phenotypic switch of remaining MAMs toward a pro-inflammatory, M1-like phenotype." (PMID 31331034, 2019). "In pancreatic cancer, CD11b+ Ly6Gneg Ly6Clow F480+ CD206high M2-like polarized macrophages have been observed to be more sensitive to CSF-1/CSF-1R blockade." (PMID 31331034, 2019). "Combination of anti- PD1 or anti- CTLA-4 checkpoint immunotherapy with CSF-1/CSF-1R blockade improved anti-tumour immunity and led to the regression of even established primary pancreatic tumours." (PMID 31331034, 2019). "Functional experiments in PDAC mice revealed that CSF-1, which is abundantly expressed by metastatic pancreatic cancer cells, is able to expand the population of MAMs while driving their differentiation toward an M2-like phenotype." (PMID 29903049, 2018). "In a pancreatic cancer xenograft mouse model, blockade of CSF-1 signaling reduced the number of TAMs that congregated in the tumor tissue and inhibited tumor growth, indicating that CSF-1 expression correlates with TAM invasion." (PMID 40940867, 2025). "In the pancreatic cancer microenvironment, various factors, such as CSF-1, IL-4, IL-13, TGFβ and IL-10, promote myeloid progenitor cell differentiation into monocytes and macrophages, which in turn secrete immunosuppressive cytokines, chemokines and enzymes, such as TGFβ, IL-10, CCL17, and CCL22." (PMID 39195299, 2024). "In addition, the activation of MAPK, PI3K-Akt, YAP-TAZ, and JAK-STAT3 signaling pathways by Kras in pancreatic cancer cells results in the upregulation of various suppressive cytokines and chemokines, such as IL-4, IL-6, IL-13, CSF1, and MCP-140,41." (PMID 37184030, 2023). "Moreover, PI3K-γ and colony-stimulating factor-1 (CSF-1) or CSF-1 receptor (CSF-1R) pathways are also involved in the infiltration and polarization of the M2 TAMs in pancreatic cancer." (PMID 36297467, 2022).
pancreatic cancer (continued). "Another major source of IL-6 is tumor-associated macrophages (TAMs), which secrete additional cytokines, such as IL-10, IL-34 and colony-stimulating factor 1 (CSF1), all of which contribute to chemoresistance in breast, lung, colorectal, prostate and pancreatic cancers." (PMID 33918653, 2021). "Investigation of the expression of CSF1R and its ligand, CSF1, indicating that CSF1 is frequently expressed by pancreatic cancer cells whereas CSF1R expression is limited to cells in the tumor microenvironment, suggesting a tumor cell/tumor microenvironment interaction." (PMID 30003190, 2018). "In human pancreatic tumors, GM-CSF (or CSF-2) is prominently expressed, compared to CSF-1." (PMID 27191744, 2016). "In addition, blockade of CSF-1/CSF1-R by mAb anti-CSF1 or with PLX2297 (a small molecule targeting the tyrosine kinase domain of CSF1-R) was reported to reprogram remaining TAMs at the tumor site to support antitumor immunity in pancreatic cancer mouse models." (PMID 28769933, 2017). "For instance, the fibroblasts-derived CSF-1, IL-6 and CCL2 has been found to promote macrophages infiltration and M2 phenotype polarization process in pancreas cancer." (PMID 37325617, 2023). "For example, the high-density of the ECM in breast and pancreatic cancers activates tumor cells and CAFs that secrete the monocyte cytokines CCL2 and colony-stimulating factor 1 (CSF-1)." (PMID 33066357, 2020). "In an experimental study in experimental pancreatic cancer on mice, the combination of anti-PD-1 with anti-CTLA-4 resulted in higher T cell infiltration and tumor response, while blocking CSF-1/CSF-1R resulted in elevated PD-1/PD-L1 expression on TAMs and increased CTLA-4 expression on CD8+ T cells." (PMID 38541123, 2024). "Moreover, SLC40A1 expression positively correlates with the expression of TAM genes (CD68, MRC1, IL10, CSF1, and CSF1R) in pancreatic tumors." (PMID 36333531, 2022). "In pancreatic cancer, α-SMA+ vimentin+ glial fibrillary acidic protein+ (GFAP), CAFs secret macrophage colony-stimulating factor 1 (M-CSF), IL-6, and CC-chemokine ligand 2 (CCL2) to promote monocyte recruitment encourage macrophage differentiation and M2 polarization." (PMID 31462327, 2019). "The mouse model of pancreatic cancer without Csf1 gene had a significant decrease in angiogenesis and reduction in tumor number." (PMID 23593148, 2013).